CRLF2 (cytokine receptor like factor 2)
Description:
Receptor for thymic stromal lymphopoietin (TSLP). Forms a functional complex with TSLP and IL7R which is capable of stimulating cell proliferation through activation of STAT3 and STAT5. Also activates JAK2 (By similarity). Implicated in the development of the hematopoietic system.
Synonyms: CRL2; TSLPR; CRLF2Y
Tractability: Antibody: UniProt places it where antibodies can reach, with high confidence; its Gene Ontology location is reachable by antibodies, with high confidence; UniProt predicts a signal peptide or a membrane-spanning region; the Human Protein Atlas places it where antibodies can reach. PROTAC: ubiquitination databases record sites on it.
Gene: Protein-coding gene on chromosome X (1,190,490 to 1,212,723, reverse strand). Ensembl gene ENSG00000205755.
Subcellular location: Cell membrane (Isoform 1); Secreted (Isoform 2)
Subcellular location (Human Protein Atlas): Plasma membrane
Pathways (Reactome):
Immune System: Interleukin-7 signaling
Gene Ontology:
Molecular function: coreceptor activity; cytokine receptor activity; cytokine binding
Biological process: cytokine-mediated signaling pathway; positive regulation of cell population proliferation; positive regulation of interleukin-5 production; positive regulation of mast cell activation; positive regulation of receptor signaling pathway via STAT
Cellular component: external side of plasma membrane; plasma membrane; receptor complex; extracellular region
Cancer hallmarks: angiogenesis (promotes); escaping immune response to cancer; proliferative signalling (promotes)
Homologues: Orthologues: chimpanzee CRLF2 (95% identical), macaque CRLF2 (86% identical), dog CRLF2 (62% identical), mouse Crlf2 (34% identical), rat Crlf2 (31% identical), zebrafish lifra (13% identical), zebrafish ghrb (13% identical), zebrafish lifrb (12% identical), zebrafish ghra (11% identical), zebrafish il11ra (9% identical), zebrafish il6r (9% identical). Paralogues in human: IL6ST (16% identical), IL31RA (15% identical), GHR (15% identical), PRLR (15% identical), IL12RB2 (14% identical), LIFR (14% identical), IL13RA1 (13% identical), OSMR (13% identical), CRLF1 (12% identical), IL13RA2 (12% identical), LEPR (11% identical), CSF3R (11% identical), and 11 more.
Diseases named in the same sentence as CRLF2 in open-access papers:
CRLF2 is named in the same sentence as 39 diseases in open-access papers, as found by Europe PMC text mining. Sharing a sentence is not in itself a finding about the gene and the disease. The quoted sentences say what the papers report.
acute lymphoblastic leukemia (33 papers, 2012 to 2025). Leukemia with an acute onset, characterized by the presence of lymphoblasts in the bone marrow and the peripheral blood. "CRLF2 rearrangements are overexpressed in approximately 50–60 % of Down syndrome-associated acute lymphoblastic leukemia (DS-ALL) cases." (PMID 40787610, 2025). "This included the CRLF2 locus that is often involved in chromosomal translocations associated with a subtype of acute lymphoblastic leukemia (ALL) that disproportionately affects Latin Americans (LAs)." (PMID 37790327, 2023). "The overexpression of CRLF2 has already been reported to be associated with acute lymphoblastic leukemia." (PMID 29697361, 2018). "This diagnostic blind spot carries significant clinical implications, as IGH::CRLF2 rearrangements are enriched in Ph-like B-cell acute lymphoblastic leukemia (Ph-like B-ALL) and have been associated with high-risk disease features and poor clinical outcomes." (PMID 41228238, 2025). "CRLF2 rearrangements occur in >50% of Ph-like and Down syndrome (DS)-associated B-acute lymphoblastic leukemia (ALL) and induce constitutive kinase signaling targetable by the JAK1/2 inhibitor ruxolitinib under current clinical investigation." (PMID 39681640, 2025). "This includes the CRLF2 locus that is often involved in translocations associated with a subtype of acute lymphoblastic leukemia (ALL) that disproportionately affects Hispanics, particularly those with Latin American ancestry." (PMID 39068148, 2024). "Cytokine receptor-like factor 2 B-cell acute lymphoblastic leukemia (CRLF2 B-ALL) is a high-risk subtype characterized by CRLF2 overexpression with poor survival rates in children and adults." (PMID 36613920, 2022). "Down syndrome acute lymphoblastic leukemia (DS‐ALL) is characterized by high frequency of CRLF2‐rearrangements, JAK2‐mutations, or RAS‐pathway mutations." (PMID 33247204, 2021). "Genetic alterations leading to overexpression of CRLF2 have been shown to be associated with pediatric acute lymphoblastic leukemia (ALL)." (PMID 32085659, 2020). "We previously discovered a mutant allele of the CRLF2 cytokine receptor by screening cDNA libraries generated from primary acute lymphoblastic leukemias (ALL), which multiple groups concurrently identified as an important oncogene in poor-risk ALL." (PMID 23145123, 2012). "Philadelphia-like acute lymphoblastic leukemia (Ph-like ALL) is a high-risk subtype, with approximately half of cases characterized by CRLF2 overexpression and frequent concomitant IKZF1 deletions." (PMID 38370004, 2024). "Overexpression of CRLF2 in leukemia has been reported and was correlated with poor outcome in pediatric acute lymphoblastic leukemia (ALL)." (PMID 27391346, 2016). "High expression levels of CRLF2 in both B-cell acute lymphoblastic leukemia (B-ALL) and T-cell acute lymphoblastic leukemia (T-ALL) are often correlated with poor prognosis and resistance to treatment." (PMID 40787610, 2025). "Recent studies have identified that BET inhibition can reverse CRLF2 overexpression in early T-cell precursor acute lymphoblastic leukemia (ETP-ALL) cell lines, suggesting a link with PRC2 dysfunction." (PMID 40787610, 2025). "CRLF2 abnormalities are prevalent in Hispanics from the U.S. and Mexican children with pre-B acute lymphoblastic leukemia (ALL)." (PMID 40421094, 2025). "Overexpression of the cytokine receptor-like factor 2 (CRLF2) gene is the most common feature in the Philadelphia chromosome (Ph)-like subtype of B-cell acute lymphoblastic leukemia (B-ALL)." (PMID 38023153, 2023). "Patients with cytokine receptor-like factor 2 rearranged (CRLF2-re) subgroup Philadelphia chromosome–like B-cell acute lymphoblastic leukemia (Ph-like B-ALL) have a high relapse rate and poor clinical outcomes." (PMID 29487712, 2018). "Children with B-cell precursor acute lymphoblastic leukemia (BCP-ALL) overexpressing the CRLF2 gene (hiCRLF2) have poor prognosis." (PMID 29796158, 2018).
acute lymphoblastic leukemia (continued). "The proposed example on CRLF2 expression in acute lymphoblastic leukemia shows that in some clinical applications methods based on sensitivity and specificity may lead to unsatisfactory cut-points due to a moderate discrimination potential of the biomarker, as represented by the whole ROC curve." (PMID 25887743, 2015). "Notably, combining ruxolitinib with standard treatment drugs has shown significant therapeutic effects in CRLF2-rearranged Ph-like ALL acute lymphoblastic leukemia." (PMID 40787610, 2025). "The most representative example is BCR-ABL1-like acute lymphoblastic leukemia (ALL), which was first identified via hierarchical clustering of gene expression profile and a majority of them include gene fusions involving CRLF2, JAK2, and ABL gene categories." (PMID 34497767, 2021). "We prospectively examined whether surface expression of Cytokine Receptor-Like Factor 2 (CRLF2) on leukemic blasts is associated with survival and induction treatment response in pediatric B-cell precursor acute lymphoblastic leukemia (BCP-ALL) patients." (PMID 29899835, 2018). "Recent studies revealed that a substantial proportion of patients with high-risk B-cell precursor acute lymphoblastic leukemia (BCP-ALL) harbor fusions involving tyrosine kinase and cytokine receptors, such as ABL1, PDGFRB, JAK2 and CRLF2, which are targeted by tyrosine kinase inhibitors (TKIs)." (PMID 27176795, 2016). "In T‐cell acute lymphoblastic leukemia (T‐ALL) patients, Stat5 phosphorylation was induced by TSLP, although CRLF2 protein was localized intracellularly." (PMID 33890726, 2021). "Alternations involving CRLF2 and their impact on STAT5 can induce cytokine-independent survival and proliferation of early hematopoietic cells, potentially contributing to the development of B-cell precursor acute lymphoblastic leukemia (BCP-ALL)." (PMID 38999955, 2024). "Proliferation was inhibited and apoptosis was induced in vitro in B-cell acute lymphoblastic leukemia (BCP-ALL) cytokine receptor-like factor 2 (CRLF2) cell lines without the induction of death of normal hematopoietic cells." (PMID 34680353, 2021). "Overexpression of cytokine receptor-like factor 2 (CRLF2) due to chromosomal rearrangement has been observed in acute lymphoblastic leukemia (ALL) and reported to contribute to oncogenesis and unfavorable outcome in ALL." (PMID 27391346, 2016).
leukemia (32 papers, 2012 to 2025). A malignant (clonal) hematologic disorder, involving hematopoietic stem cells and characterized by the presence of primitive or atypical myeloid or lymphoid cells in the bone marrow and the blood. "The identification of IGF1R and FGFR1 as novel components of TSLP/CRLF2 signaling enhances our understanding of the molecular mechanisms that underlie TSLP-mediated leukemia proliferation." (PMID 40787610, 2025). "The JAK2 p.L884P was annotated as a somatic variant in a patient with B-ALL leukemia positive to CRLF2 rearrangement." (PMID 41009670, 2025). "Instead, rearrangements involving CRLF2 and iAMP21, which confer a high risk for leukemia, are more frequently observed among Mexican patients." (PMID 38250553, 2023). "The B cell precursor leukemia cell line MUTZ-5 from a relapsed Philadelphia-like B-ALL patient features a CRLF2-translocation leading to wt CRLF2 overexpression, as well as the JAK2R683G mutation, and the absence of mutations in any RAS-MAPK pathway genes." (PMID 33247204, 2021). "We found that the IKZF1-encoded protein, Ikaros, directly binds to the CRLF2 promoter and regulates CRLF2 expression in leukemia cells." (PMID 27391346, 2016). "We observed high expression of CRLF2 in high-risk leukemia and this correlates with the poor clinical outcome." (PMID 27391346, 2016). "Leukemias of this Ph-like subgroup frequently show gene alterations and dysregulated expression of cytokine receptor-like factor 2 (CRLF2) and activating Janus kinase (JAK) mutations." (PMID 25682198, 2015). "Therefore, understanding of the cellular and molecular mechanisms that drive CRLF2 B-ALL is critical for identifying new potential therapeutic candidates for the treatment of patients with this high-risk leukemia." (PMID 36613920, 2022). "However, mutations causing the activation of CRLF2 may also be receptor-independent prognostic factors in leukemia." (PMID 38999955, 2024). "In addition to leukemia-driving mutations, we have identified recurrent pathogenic mutations CRLF2 p.F232C (n = 7), TYK2 p.A413T (n = 7), JAK2 p.R683G (n = 4), KRAS p.G12D (n = 4), FLT3 p.Y842C (n = 3) and PTPN11 p.D61V (n = 3), previously frequently found in pediatric ALL." (PMID 34830809, 2021). "When Ph-like ALL cells from patient-derived xenografts were exposed to GCs, CRLF2-rearranged leukemia consistently exhibited reduced GC sensitivity in vitro." (PMID 40787610, 2025). "•First demonstration of TSLP's dual roles in leukemia: TSLP promotes proliferation via CRLF2 signaling while inducing apoptosis in specific contexts, revealing its paradoxical tumor-modulating effects." (PMID 40787610, 2025). "Recent studies have elucidated the diverse signaling mechanisms activated by TSLP in leukemia cells, with a particular focus on CRLF2-overexpressing Ph-like ALL cell lines." (PMID 40787610, 2025). "These translational studies demonstrate an effective two-pronged therapeutic strategy that mitigates acute CART-induced hyperinflammation and provides potential anti-leukemia ‘maintenance’ relapse prevention for CRLF2-rearranged Ph-like and DS-ALL." (PMID 39681640, 2025). "We previously developed TSLPRCART immunotherapy and reported potent preclinical in vitro and in vivo anti-leukemia activity in CRLF2-ovexpressing ALL cell lines and xenograft models." (PMID 39681640, 2025). "Additional studies demonstrated that TSLP stimulation of CRLF2-rearranged leukemia cells resulted in aberrant STAT5 and PI3K/mTOR pathway signaling." (PMID 40787610, 2025). "For example, CAR T-cells targeting the thymic stromal lymphopoietin receptor (TSLPR) eliminated leukemia in 4 acute lymphoblastic leukemia xenograft models with overexpression of human cytokine receptor like factor 2 (CRLF2)." (PMID 32526987, 2020). "Strikingly, a significant positive enrichment for the MYC gene signature was apparent in Eμ-Crlf2/Jak2R683G leukemia cells with chronic Jak2 depletion across multiple data sets (FDR < 0.01)." (PMID 29907650, 2018).
leukemia (continued). "Splenic Eμ-Crlf2/mutant Jak2 leukemia cells expressed GFP (surrogate readout of mutant Jak2 expression) and elevated cell surface Crlf2." (PMID 29907650, 2018). "Subsequent Western blot analysis of these leukemias demonstrated sustained depletion of Jak2 (lanes M4–M7), and a decrease in pStat5Y694 was observed in dsRed+ Eμ-Crlf2/Jak2P933R-pREBIR-shJak2.3323 leukemia cells harvested from moribund Dox-treated mice." (PMID 29907650, 2018). "This indicates that enhanced signaling through c-Myc in Eμ-Crlf2/Jak2R683G leukemia cells following chronic Jak2 depletion is mediated by enhanced c-Myc protein levels in the absence of any increase in mRNA levels." (PMID 29907650, 2018). "Flow cytometric analysis of bone marrow-derived leukemia cells revealed that 7.51% (29/286) of 386 pediatric BCP-ALL patients were CRLF2-positive (CRLF2pos) at diagnosis." (PMID 29899835, 2018). "Here, we developed genetically engineered mouse models (GEMMs) of CRLF2/JAK2 mutant B-ALLs and used a pharmacogenomics approach to delineate the functional role of JAK2 in these leukemias and human CRLF2-rearranged/JAK2I682F-expressing MHH-CALL4 B-ALLs." (PMID 29907650, 2018). "Our data along with emerging literature in leukaemia highlight a role for the focal adhesion pathway in CRLF2‐r ALL." (PMID 28033648, 2017). "Sirolimus treatment significantly inhibited leukemia proliferation in eight tested models with JAK pathway mutations and/or CRLF2 rearrangements, as well as resulted in enhanced long-term animal survival." (PMID 24904824, 2014). "In this study, we posited that combinatorial TSLPRCART and ruxolitinib would have superior activity and first validated potent TSLPRCART-induced inhibition of leukemia proliferation in vitro in CRLF2-rearranged ALL cell lines and in vivo in Ph-like and DS-ALL patient-derived xenograft (PDX) models." (PMID 39681640, 2025). "Finally, CRLF2 gene alterations or Ras pathway activation were detected as a third class of cooperating lesions to fully transform leukemia cells and affecting functions such as cytokine receptors and associated kinases." (PMID 33890726, 2021). "Additionally, phase 1/2 trials of CAR T cells targeted against CD22 are underway, as well as preclinical work to identify other potential leukemia protein targets such as CRLF2, mixed lineage leukemia (MLL), and CD123." (PMID 30670684, 2019). "Eleven of the 19 Ph-like leukemias were positive for CRLF2 rearrangements." (PMID 31318944, 2019). "To test this hypothesis, we exposed Ph-like ALL cells from patient-derived xenografts to GCs and found that CRLF2 rearranged (CRLF2R) leukemias uniformly demonstrated reduced GC sensitivity in vitro." (PMID 31318944, 2019). "In vivo Jak2 depletion in mice bearing Eμ-Crlf2/Jak2R683G leukemias using two different shRNAs resulted in significantly reduced peripheral WBC count, reduced leukemic burden in the spleen, and a marked survival benefit that correlated with knockdown efficiency of the Jak2 shRNAs." (PMID 29907650, 2018). "While type II JAK2 inhibitors are not currently in clinical development, other strategies aimed at complete inhibition of JAK2 (such as HSP90 inhibitors) may produce greater anti-leukemia efficacy than ruxolitinib in CRLF2-re Ph-like ALL." (PMID 29487712, 2018). "We next sought to determine whether Eμ-Crlf2/Jak2R683G leukemias with sustained knockdown of Jak2 (referred to here as “Jak2 knockdown-persistent cells”) obtained from moribund Dox-treated recipient mice maintained an ability to respond to mutant Jak2." (PMID 29907650, 2018). "The mechanisms of CRLF2 overexpression in leukemia are not fully understood." (PMID 27391346, 2016). "Initial studies using (non-CRLF2-rearranged) murine B-ALL models identified activation of PI3K/mTOR signaling in these leukemias, which was modulated by IL-7 and TSLP and could be abrogated in vitro and in vivo by sirolimus treatment." (PMID 24904824, 2014).